TM7SF2 (transmembrane 7 superfamily member 2)
Description:
Catalyzes the reduction of the C14-unsaturated bond of lanosterol, as part of the metabolic pathway leading to cholesterol biosynthesis.
Synonyms: C14SR; ANG1; DHCR14A; NET47
Tractability: Antibody: its Gene Ontology location is reachable by antibodies, with high confidence; UniProt predicts a signal peptide or a membrane-spanning region. PROTAC: ubiquitination databases record sites on it; its protein half-life has been measured.
Target class: Enzyme; Oxidoreductase
Gene: Protein-coding gene on chromosome 11 (65,111,845 to 65,116,384, forward strand). Ensembl gene ENSG00000149809.
Subcellular location: Microsome membrane; Endoplasmic reticulum membrane
Subcellular location (Human Protein Atlas): Endoplasmic reticulum; Vesicles
Pathways (Reactome):
Metabolism: Activation of gene expression by SREBF (SREBP); Cholesterol biosynthesis via desmosterol (Bloch pathway); Zymostenol biosynthesis via lathosterol (Kandutsch-Russell pathway)
Gene Ontology:
Molecular function: Delta14-sterol reductase activity; protein binding; NADP binding; oxidoreductase activity, acting on the CH-CH group of donors, NAD or NADP as acceptor
Biological process: cholesterol biosynthetic process; sterol biosynthetic process
Cellular component: endoplasmic reticulum; endoplasmic reticulum membrane; receptor complex; nuclear inner membrane; plasma membrane; membrane
Genetic constraint (gnomAD): Loss-of-function variants: 51 observed, 49.46 expected, observed/expected ratio (o/e) 1.03, 90% interval 0.82 to 1.3. The upper end of that interval is the gene's LOEUF score, 1.3, which puts it in group 5 of 6, group 1 being the genes least tolerant of losing a copy. Missense variants: 541 observed, 525.93 expected, observed/expected ratio (o/e) 1.03, 90% interval 0.96 to 1.1. Synonymous variants: 255 observed, 227.69 expected, observed/expected ratio (o/e) 1.12, 90% interval 1.01 to 1.24.
Homologues: Orthologues: chimpanzee TM7SF2 (99% identical), macaque TM7SF2 (97% identical), pig TM7SF2 (92% identical), dog TM7SF2 (89% identical), rat Tm7sf2 (87% identical), mouse Tm7sf2 (86% identical), guinea pig TM7SF2 (85% identical), tropical clawed frog tm7sf2 (64% identical), zebrafish tm7sf2 (64% identical). Paralogues in human: LBR (58% identical), DHCR7 (38% identical).
Diseases named in the same sentence as TM7SF2 in open-access papers:
TM7SF2 is named in the same sentence as 35 diseases in open-access papers, as found by Europe PMC text mining. Sharing a sentence is not in itself a finding about the gene and the disease. The quoted sentences say what the papers report.
cervical cancer (6 papers, 2021 to 2025). A primary or metastatic malignant neoplasm involving the cervix. "As a key enzyme in cholesterol synthesis, TM7SF2 has been implicated in lipid metabolic reprogramming and the progression of cervical cancer." (PMID 40860196, 2025). "The mechanism and underlying signaling pathway of TM7SF2 via CPT1A associated lipid metabolism in cervical cancer development were explored using Western blotting, IHC, colony formation, transwell assay, and wound healing assay." (PMID 38693136, 2024). "To gain insights into the underlying mechanisms of TM7SF2 in cervical cancer, we conducted a GSEA analysis, which revealed a significant association between CPT1A and the WNT signaling pathway." (PMID 38693136, 2024). "In our current study, the expression levels of TM7SF2 and its related carcinogenic effects and underlying biological mechanisms in cervical cancer were uncovered." (PMID 34667152, 2021). "Additionally, TM7SF2 has been implicated in a range of human diseases, such as Greenberg’s dysplasia, CK syndrome, skin papilloma, and cervical cancer, highlighting its importance in physiological regulation and pathological diagnosis." (PMID 39996914, 2025). "The present study is the first to report the association between TM7SF2 and cervical cancer." (PMID 33997099, 2021). "In the context of cervical cancer, recent findings indicate a link between the activation of the TM7SF2/C-Raf/MEK/ERK pathway and an increase in cell proliferation and migration." (PMID 39996914, 2025). "A previous study reported that TM7SF2 suppression inhibited the C-Raf/ERK1/2 pathway in cervical cancer." (PMID 39996914, 2025). "Our previous studies found that upregulation of TM7SF2, which works as an enzyme involved in the process of cholesterol biosynthesis expression, was highly correlated with cervical cancer." (PMID 38693136, 2024). "Our previous findings elucidated a novel mechanism of TM7SF2 expediting the disease progression that TM7SF2 overexpression promoted cervical cancer cell proliferation and invasion in vitro and in vivo." (PMID 38693136, 2024). "This study put forward an idea that TM7SF2-induced lipid reprogramming promotes proliferation and migration via CPT1A/Wnt/β-Catenin axis in cervical cancer, underlying the progression of cervical cancer." (PMID 38693136, 2024). "We have previously identified 7 key genes including TM7SF2 that were significantly elevated in HPV-negative cervical cancer cells and tissues." (PMID 38693136, 2024). "Crucially, our research identified a central role for TM7SF2 in mediating CPT1A’s function in cervical cancer." (PMID 38693136, 2024). "The study was initiated by successfully establishing TM7SF2-overexpressed and TM7SF2-knockout cell lines in C33A and SiHa cervical cancer cell lines." (PMID 38693136, 2024). "Our study built upon this expanding understanding of TM7SF2’s functions by shedding light on its significant contributions to cervical cancer progression." (PMID 38693136, 2024). "Lastly, upregulation of CPT1A partially reversed the suppression of WNT3A, β-catenin, and c-Myc protein expression mediated by TM7SF2-knockout, suggesting that TM7SF2 regulated the WNT/β-catenin signaling via CPT1A in cervical cancer cells." (PMID 38693136, 2024). "Generally, our study highlights the significance of TM7SF2 in cervical cancer tumorigenesis through its role in regulating lipid metabolism." (PMID 38693136, 2024). "Above all, these findings revealed that TM7SF2 overexpression obviously promoted migration and invasion of cervical cancer cells." (PMID 34667152, 2021). "The immunohistochemistry staining results indicated that the expression of TM7SF2 was increased in cervical cancer tissues in comparison with the corresponding normal tissues adjacent to the cancer." (PMID 34667152, 2021). "In summary, TM7SF2 promoted tumor growth and inhibited apoptosis in vivo, contributing to the progression of cervical cancer." (PMID 34667152, 2021).
cervical cancer (continued). "In our study, we found that the expression of TM7SF2 mRNA and protein was upregulated in cervical cancer cells compared with normal cervical epithelial cells." (PMID 34667152, 2021). "Due to the relatively high expression of TM7SF2 in C33A cell line, we established a stable TM7SF2-knockout C33A cell line to figure out the biological functions of TM7SF2 in cervical cancer." (PMID 34667152, 2021). "Next, in order to further illustrate the biological mechanism of TM7SF2 via C-Raf-ERK pathway in the progression of cervical cancer, we used an inhibitor to suppress the C-Raf/ERK1/2 pathway." (PMID 34667152, 2021). "Consistently, TM7SF2 protein was increased in cervical cancer tissues compared with its corresponding adjacent normal cervical tissues." (PMID 34667152, 2021). "In order to further figure out the function of TM7SF2 in cervical cancer cells, TM7SF2-knockout and TM7SF2-overexpressing cells were constructed in C33A and SiHa cells." (PMID 34667152, 2021). "The expression of TM7SF2 at mRNA and protein levels was notably elevated in cervical cancer cells compared with Ect1/E6E7 cells by use of RT-PCR and western blotting." (PMID 34667152, 2021). "In conclusion, TM7SF2 expression was evidently increased in human cervical cancer tissues and cells." (PMID 34667152, 2021). "In this study, the immunohistochemistry (IHC) assay, real-time RT-PCR and western blotting analysis were used to determine the TM7SF2 expression in cervical cancer tissues." (PMID 34667152, 2021). "Meanwhile, the overexpression of C33A cells was also established in order to further explore the effects of TM7SF2 on cervical cancer cells." (PMID 34667152, 2021). "Subsequently, the oncogenic role of the upregulation of TM7SF2 in cervical cancer C33A and SiHa cell lines was also identified by our previous study, in which TM7SF2 regulated proliferation and apoptosis of cervical cancer cells via C-Raf/ERK pathway regulation." (PMID 38693136, 2024). "However, the mechanistic basis of TM7SF2 promoting cervical cancer progression via lipid metabolism remains poorly understood." (PMID 38693136, 2024). "This study found that TM7SF2 could promote the fatty acids level and lipid droplet accumulation in cervical cancer, implying the novel role of TM7SF2 in the lipid reprogramming of tumorigenesis." (PMID 38693136, 2024). "In summary, we reported that the tumor promotive functions of TM7SF2 in cervical cancer." (PMID 34667152, 2021). "LY3009120 abrogated the promotive effect of TM7SF2 on cervical cancer cells." (PMID 34667152, 2021). "The regulation of C-Raf/ERK1/2 signaling pathway by TM7SF2 was confirmed in cervical cancer cells." (PMID 34667152, 2021). "To figure out the underlying mechanism of TM7SF2 in cervical tumorigenesis, we further investigated that whether C-Raf/ERK1/2 signaling pathway is involved in TM7SF2-induced cervical cancer." (PMID 34667152, 2021). "Next, we used multiple methods to determine the ability of cell proliferation, migration, invasion, apoptosis, and cell cycle in cervical cancer cells after TM7SF2 modulation, such as CCK8 assay, colony formation assay, Transwell assay, wound healing assay, and flow cytometry." (PMID 34667152, 2021). "Consistently, the opposite effects were observed after TM7SF2 knockout in cervical cancer cells." (PMID 34667152, 2021). "The results of our study suggest that TM7SF2/C-Raf/ERK1/2 axis exerts an essential effect on the progression of cervical cancer and targeting TM7SF2 may be a promising method to treat cervical cancer." (PMID 34667152, 2021). "We further explored whether TM7SF2 contributed to motility of cervical cancer cells." (PMID 34667152, 2021). "TM7SF2 is an essential molecule involving in the activation of C-Raf-ERK pathway and then promotes cell growth and inhibited apoptosis in cervical cancer, indicating that inhibition of TM7SF2 may be a therapeutic strategy in the future for cervical cancer patients." (PMID 34667152, 2021).
cervical cancer (continued). "The expression of TM7SF2 at the transcriptional and translational levels was detected in normal cervical epithelial cell line Ect1/E6E7 and cervical cancer cell lines, including C33A, SiHa, CaSki, and HeLa." (PMID 34667152, 2021). "Hence, TM7SF2 may be an oncogene in cervical cancer by in vivo and vitro experiments." (PMID 34667152, 2021). "Therefore, TM7SF2 could serve as a therapeutic target in future cervical cancer treatment." (PMID 34667152, 2021). "Further, we found that TM7SF2 participated in promoting tumorigenesis and progression via activation of C-Raf/ERK pathway in cervical cancer, which can be partly reversed by Raf inhibitor LY3009120." (PMID 34667152, 2021). "Moreover, TM7SF2 directly bonded with CPT1A, a key enzyme in fatty acid oxidation, and regulated CPT1A protein expression in cervical cancer cells." (PMID 38693136, 2024). "In this study, the authors discovered the multiple genes in HPV-negative cervical cancer, including PRAME, HMGA2, ETV4, MEX3A, TM7SF2, SLC19A1, and TTYH3, which could contribute to HPV-negative cervical cancer development." (PMID 33997099, 2021). "Furthermore, it is necessary to investigate whether TM7SF2 suppression also inhibits the C-Raf/ERK1/2 pathway in colorectal cancer, as observed in cervical cancer." (PMID 39996914, 2025). "Notably, changes in CPT1A protein expression did not impact TM7SF2 protein expression level when CPT1A was overexpressed in cervical cancer cells, suggesting that CPT1A might function as a downstream effector of TM7SF2." (PMID 38693136, 2024). "However, there is no clear understanding of how TM7SF2 regulates cervical cancer lipid reprogramming." (PMID 38693136, 2024). "Based on our results, TM7SF2 was expressed at higher levels in the C33A cell line and HPV-negative tissues than in HPV-positive, normal cell lines and tissues, implying that TM7SF2 may also play a specific role in the development of HPV-negative cervical cancer." (PMID 33997099, 2021).
skin papilloma (4 papers, 2015 to 2022). A benign papillary neoplastic growth on the skin composed of epithelial cells and a fibrous stalk. "In the present study, we found that the loss of the Tm7sf2 gene markedly increases size, incidence and multiplicity of skin papillomas by altering skin cholesterol levels in a mouse model of skin carcinogenesis." (PMID 25804527, 2015). "We found that the loss of Tm7sf2 increased incidence and multiplicity of skin papillomas." (PMID 25804527, 2015). "Apart from its clear enzymatic role in cholesterol biosynthesis, Tm7sf2 has been shown to be important for liver regeneration, in skin papilloma formation, and affecting nuclear factor kappa B (NF-κB) activity and TNFα expression." (PMID 33330474, 2020).
follicular carcinomas (2 papers, 2021 to 2024). "Also, TM7SF2’s involvement in tumorigenesis, particularly in differentiating non-aggressive and aggressive follicular carcinomas in the thyroid, underscored its potential as a diagnostic biomarker in cancer management." (PMID 38693136, 2024).
Greenberg skeletal dysplasia (2 papers, 2016 to 2020). "Mutations in TM7SF2 cause Greenberg skeletal dysplasia (a.k.a. hydrops-ectopic calcification-moth-eaten or HEM skeletal dysplasia), an autosomal recessive chondrodystrophy characterized by fetal hydrops, short limbs, and abnormal chondro-osseous ossification." (PMID 33256181, 2020).
Insulin resistance (2 papers, 2020 to 2024). Increased resistance towards insulin, that is, diminished effectiveness of insulin in reducing blood glucose levels. "Dysregulation of TM7SF2 function may contribute to metabolic abnormalities and diseases, including dyslipidemia, insulin resistance and obesity." (PMID 39359475, 2024). "As might be expected from their function in insulin pathways, the Tm7sf2–/– animals exhibited a mild insulin resistance phenotype." (PMID 33330474, 2020).
Obesity (2 papers, 2020 to 2024). Accumulation of substantial excess body fat. "Akt levels themselves were not appreciably altered in the KO, but Akt phosphorylation was strongly inhibited in Tm7sf2-KO liver, indicating a possible defective insulin signaling that could lead to obesity and diabetes." (PMID 33330474, 2020).
cervical (1 paper, 2024). "In this study, the molecular mechanisms of TM7SF2 via CPT1A in the process of cervical tumorigenesis were explored." (PMID 38693136, 2024). "Furthermore, whether WNT/β-catenin signaling pathway participated in TM7SF2 mediated cervical tumorigenesis via CPT1A was explored." (PMID 38693136, 2024).
colorectal cancer (1 paper, 2025). A primary or metastatic malignant neoplasm that affects the colon or rectum. "Cox regression analysis also demonstrated that higher TM7SF2 expression was significantly associated with decreased patient survival, suggesting that TM7SF2 may serve as an independent prognostic factor in colorectal cancer." (PMID 39996914, 2025). "Furthermore, TM7SF2 expression was also elevated in cases with distant metastasis, suggesting that increased TM7SF2 expression may be associated with a more aggressive tumor phenotype in colorectal cancer." (PMID 39996914, 2025). "The proliferation, migration, invasion, and colony-forming abilities of TM7SF2-silenced cells were compared with those of colorectal cancer cells with intact TM7SF2 expression." (PMID 39996914, 2025). "Chi-square analysis demonstrated a significant increase in the proportion of patients with advanced clinical stages of colorectal cancer among those with high TM7SF2 expression." (PMID 39996914, 2025). "Despite these insights, the specific role of TM7SF2 in colorectal cancer remains an area for further exploration and research." (PMID 39996914, 2025). "In this study, TM7SF2 expression was silenced using siRNA in the colorectal cancer cell lines SW480 and SW620." (PMID 39996914, 2025). "In conclusion, the findings of this study highlight the potential of TM7SF2 as a metastatic biomarker and therapeutic target in colorectal cancer." (PMID 39996914, 2025). "In this study, analyses using patient tissues and cell lines confirmed that TM7SF2 plays a crucial role in colorectal cancer." (PMID 39996914, 2025). "A WST-1 assay was conducted to examine the impact of TM7SF2 downregulation on the proliferation of colorectal cancer cells." (PMID 39996914, 2025). "This study investigates the correlation between TM7SF2 expression and the prognosis of colorectal cancer patients." (PMID 39996914, 2025). "Furthermore, we demonstrate that the downregulation of TM7SF2 in colorectal cancer cell lines inhibits key cancer cell functions, highlighting its potential role as a therapeutic target." (PMID 39996914, 2025). "However, in colorectal cancer tissues, TM7SF2 exhibited strong expression in the plasma membrane and cytoplasm." (PMID 39996914, 2025). "Therefore, TM7SF2 shows promise as a biomarker for the prevention of colorectal cancer." (PMID 39996914, 2025). "The migration and invasion abilities of colorectal cancer cells were assessed by comparing the TM7SF2 knockdown group with the negative control group." (PMID 39996914, 2025).
E. coli infection (1 paper, 2018). "Importantly, based on our results, E. coli infection causes down-regulation of genes encoding lipid biosynthesis enzymes including ALOX15, FASN, GPAM, TM7SF2 that are involved in milk production." (PMID 29470489, 2018).
endotoxemia (1 paper, 2015). "Here we showed, for the first time, that the loss of the Tm7sf2 gene, primarily involved in cholesterol biosynthesis, attenuates the extent of renal injury in a model of experimental endotoxemia and kidney failure, induced by the administration of LPS." (PMID 26540160, 2015).
fibrosarcoma (1 paper, 2020). A malignant mesenchymal fibroblastic neoplasm affecting the soft tissue and bone. "Critically, the genes under Tm7sf2 radial genome positional regulation in primary mouse liver cells exhibited minimal overlap with genes under TM7SF2 regulation in the human HT1080 fibrosarcoma cancer cell line." (PMID 33330474, 2020).
gout (1 paper, 2024). A condition characterized by painful swelling of the joints, which is caused by deposition of urate crystals. "We also discovered a significant correlation between mast cell TM7SF2 expression and gout risk (beta = 1.34)." (PMID 38831441, 2024). "The role of TM7SF2 is more directly associated with the metabolic characteristics of gout." (PMID 38831441, 2024). "The study also found that genes such as TRIM46, MAP3K11, KRTCAP2, and TM7SF2 could potentially elevate the risk of gout." (PMID 38831441, 2024). "This study also identified 22 methylation sites related to gout, and genes that may increase the risk of gout, such as TRIM46, MAP3K11, KRTCAP2 and TM7SF2." (PMID 38831441, 2024). "Finally, we found by single-cell analysis that MAP3K11, KRTCAP2, PCNX3, and TM7SF2 demonstrate potential significant roles in the pathogenesis of gout." (PMID 38831441, 2024). "As a factor influencing cholesterol synthesis, TM7SF2 could regulate the levels of cholesterol in cells and tissues, impacting the functionality of inflammatory cells and the production of inflammatory mediators, thereby playing a role in the pathology of gout." (PMID 38831441, 2024).